HIF1A (hypoxia inducible factor 1 subunit alpha)
Diseases named in the same sentence as HIF1A in open-access papers (continued):
Sharing a sentence is not in itself a finding about the gene and the disease.
pancreatic adenocarcinoma (21 papers, 2015 to 2026). "The authors found that monocytes terminally differentiate into two TAM populations, defined by Trem2 or Hif1a expression, in a murine model of pancreatic adenocarcinoma." (PMID 40523200, 2025). "Other study shows MIF induced by hypoxia in pancreatic adenocarcinoma is necessary for maximal hypoxia-induced HIF1α expression." (PMID 38685050, 2024). "DUOXs enzymes seem to regulate epithelial mesenchymal transition (EMT), invasiveness, and the induction of endothelial growth factor (VEGF) and hypoxia-inducible factor 1-alpha (HIF-1α) in pancreatic adenocarcinoma cell line." (PMID 33535472, 2021). "EVs derived from hypoxia pancreatic adenocarcinoma cells transported miR-301a-3p in a HIF1a- or HIF2a-dependent manner, induced macrophage M2 polarization through activation of the PTEN/PI3Kγ signaling pathway, and thus promoted lung metastasis of pancreatic adenocarcinoma cells." (PMID 37046819, 2023). "In conclusion, the hyperthermia of pancreatic adenocarcinoma cells in vitro affects endothelial cells under defined environmental conditions (cell-to-cell contact, oxygen status, treatment temperature), with HIF-1α and VEGF secretion playing a role in a complex context." (PMID 37626752, 2023). "Taken together, the hyperthermia of pancreatic adenocarcinoma cells in vitro impacts endothelial cells under defined environmental conditions (cell-to-cell contact, oxygen status, treatment temperature), whereby HIF-1α and VEGF secretion play a role in a complex context." (PMID 37626752, 2023). "circUBAP2 modulates pancreatic adenocarcinoma tumorigenesis by regulating the levels of hsa-miR-494 and the expression of CXCR4, HIF1A, ZEB1, SDC1, and TWIST132." (PMID 33707417, 2021). "Forced expression of miR-145 inhibited the cell viability, migration, HIF-1α, VEGF expression and enhanced the chemosensitivity to gemcitabine through its direct target p70S6K1 in pancreatic adenocarcinoma." (PMID 27765914, 2016). "To investigate the relationship between HIF-1α and SCF in PDAC, we examined their expression pattern in human pancreatic adenocarcinoma tissue." (PMID 25799412, 2015). "Moreover, the online database (ChIPbase) demonstrated an obvious correlation between HIF-1α and FOXC2 mRNA expression in pancreatic adenocarcinoma (PDDA)." (PMID 31367258, 2019). "Although the role of HIF-1α in placental glycosylation remains unknown, indirect evidence in tumor tissues indicates that HIF-1α upregulation increased fucosyltransferases (FUT)-1-2 mRNA levels and overexpression of fucosylated proteins on the surface of pancreatic adenocarcinoma cells." (PMID 37206444, 2023). "In human pancreatic adenocarcinoma cells, lipoprotein depletion in the cell culture medium leads to the activation of the HIF-1α pathways, but the addition of LDLs, the main cholesterol transporters in the plasma, inhibits the accumulation of HIF-1α by regulating the activity of PHDs enzymes." (PMID 35386720, 2022). "It was identified that the expressions of CXCR4, HIF1A, ZEB1, and SDC1 in pancreatic adenocarcinoma (PAAD) were controlled by circ-UBAP2 and miR-494." (PMID 32665846, 2020). "Furthermore, forced expression of p70S6K1 in miR-145-over-expressing pancreatic adenocarcinoma cells restored the expression levels of HIF-1α and VEGF which were inhibited by miR-145, suggesting that miR-145 controls expression of HIF-1a and VEGF by targeting p70S6K1 in the cells." (PMID 27765914, 2016).
ischemic disease (20 papers, 2012 to 2025). Lack of blood supply to an area of the body, resulting in impairment of tissue oxygenation. "Accumulating evidence suggests that the mTOR/HIF‐1α pathway is associated with ischemic diseases such as ischemic myocardial infarction due to its pro‐angiogenic effect." (PMID 40032632, 2025). "HIF-1α is involved in the pathological process and inflammatory reactions associated with ischemic disease." (PMID 34594389, 2021). "Comprehending the pro-inflammatory T-cell response and anti-tumor immunity, along with the role of metabolic regulation through HIF-1α in chronic inflammation, cancer, and ischemic diseases, is crucial for developing therapeutic approaches." (PMID 39099978, 2024). "Maintaining HIF1α level during the late-stage of ischemic diseases benefits to the therapy of the disease." (PMID 39707436, 2024). "DMOG, an inhibitor of PHD, can stabilize HIF-1α and mimic true hypoxic conditions, which in turn participates in the repair of ischemic diseases." (PMID 37189610, 2023). "HIF-1α is considered to be an important regulator of various physiological and pathophysiological conditions, such as cancer and ischemic diseases 11-13." (PMID 35547748, 2022). "HIF‐1α signaling‐regulated factors were analyzed to determine whether the APCS group cells improved ischemic disease treatment in terms of angiogenesis relative to currently existing cell therapies." (PMID 40278796, 2025). "In sum, this study adds a layer to our understanding of the role of HIF-1α in human vascular cell homeostasis and angiogenesis, and identifies a new and potentially targetable mechanism for development of therapeutic interventions against ischemic diseases." (PMID 37158785, 2024). "Using small molecules as HIF-1α-targeting drugs requires selective delivery of these drugs to the target tissues or cells, which becomes a challenge if it is systemic administration for diseases such as cancer or ischemic diseases." (PMID 39099978, 2024). "Thus, by escalating knowledge on HIF-1α control, increased literature about HIF-1α control and influence can lead to the development of improved treatment for ischemic diseases, inflammatory diseases, and cancer." (PMID 39099978, 2024). "The critical role of HIF1α in treating ischemic diseases has been emphasized." (PMID 39707436, 2024). "HIF-1α has been proven to be a key molecule in many hypoxic-ischemic diseases and tumorigenesis." (PMID 37865653, 2023). "Many groups have investigated potential therapies of ischemic disease with HIF-1α in rat models." (PMID 22403648, 2012). "Therefore, in view of the important role of HIF-1α in various ischemic diseases, it may provide a new and effective therapeutic approach for diseases characterized by hypoxia, which has attracted extensive attention of scholars." (PMID 35684364, 2022). "Growing evidence suggests that hypoxia-inducible factor-1 alpha (HIF-1α) is a major regulator of cellular and systemic homeostatic response to hypoxia and plays an essential role in pathophysiology of ischemic disease." (PMID 28724891, 2017). "In this condition, spheroids grew faster than monolayer culture and, focusing the attention on the treatment of the ischemic disease, the authors found increased expression levels of survival factors (CXCL12 and HIF‐1a) in response to the size of the spheroids." (PMID 36209478, 2022).
ovarian tumor (20 papers, 2008 to 2023). "Furthermore, the expression level of HIF-1α is associated with chemoresistance in a metastatic and aggressive ovarian tumor." (PMID 35464826, 2022). "HIF-1α acts as a transcription factor to regulate a variety of proteins, thereby promoting the development of ovarian tumours." (PMID 35004308, 2021). "Melatonin can bind MT1 receptors to reduce VEGFR2 and hypoxia-inducible factor (HIF)-1α in ovarian tumour cells; this finding is in contrast to the results observed in this study with normal cells." (PMID 30864638, 2019). "The immunostaining analyses indicated the presence of high levels of Twist2 and HIF-1α in the areas containing the cancer cells of the primary ovarian tumors." (PMID 23946798, 2013). "We demonstrate that LOX expression correlates with HIF-1α in 61 cases ovarian tumor tissues and that hypoxia upregulates LOX and HIF-1α expression and migration/invasion of HO8910/HO8910-PM cells via HIF-1α and HIF-2α." (PMID 23545606, 2013). "Furthermore, inhibition of HIF-1α expression in ovarian tumor cells slowed formation of tubular networks by human umbilical vein endothelial cells, suggesting inhibition of tumor-associated neo-angiogenesis." (PMID 26343197, 2015). "However, it was recently reported using Western Blot analysis that HIF-1α-expressing ovarian tumours had a significantly higher rate of response to postoperative TC chemotherapy and exhibited significantly better survival." (PMID 19014607, 2008). "Myricetin alleviates the formaldehyde-enhanced Warburg effect in tumor cells through the inhibition of human hypoxia-inducible factor 1 subunit alpha (HIF-1α), an important target in lung and ovarian tumors." (PMID 37764304, 2023). "It was also shown that ABCG2 level was increased in ovarian tumor-initiating cells (TIC/CIC/CSC) and depletion of either HIF-1α or ABCG2 reduced tumorsphere (cell aggregate) formation, demonstrating HIF-1α-to-ABCG2 axis in hypoxic tumorsphere." (PMID 30364132, 2018). "In addition, p-ERK promoted cisplatin resistance in ovarian tumors through stabilizing HIF-1α by phosphorylating PHD2, an enzyme hydroxylating HIF-1α and inducing its degradation by a ubiquitin-mediated pathway." (PMID 35264959, 2022). "In addition, we tested the protein expression of HIF‐1α or HIF‐2α and ALDH1A1 or CD133, another CSC marker, in 115 ovarian tumor tissues using immunohistochemical staining." (PMID 30536571, 2019). "In addition, we found a significant positive correlation between HIF‐2α and ALDH1A1/CD133 protein expression, but only a weak positive correlation of HIF‐1α and ALDH1A1 protein expression in 115 ovarian tumor tissue samples." (PMID 30536571, 2019). "To assess whether sMEK1 inhibits the expression of VEGF and HIF-1α via this signaling pathway, we analyzed VEGF expression in sMEK1-transfected SKOV-3 ovarian tumor cells." (PMID 26378810, 2015). "Given that ovarian tumors express high levels of stem cell factor (KIT ligand), inhibition of the c-KIT/PI3K/Akt/mTOR pathway may reduce IDO expression, and may also limit signaling through CREB, STAT3 and HIF-1α, all of which potentially contribute to immune suppression and disease progression." (PMID 26343197, 2015).
Parkinson disease (20 papers, 2010 to 2025). A progressive degenerative disorder of the central nervous system characterized by loss of dopamine producing neurons in the substantia nigra and the presence of Lewy bodies in the substantia nigra and locus coeruleus. "Treatment with MPTP, a prodrug to the neurotoxin MPP+, which causes Parkinsonism symptoms by destroying the dopaminergic neurons, was shown to inhibit HIF-1α accumulation in mice and in dopaminergic cell lines." (PMID 32973662, 2020). "HIF1A has been associated with age-related degenerative disorders, e.g. Alzheimer's and Parkinson's disease and genetic ablation of its expression significantly accelerates the onset of cellular senescence." (PMID 21179406, 2010). "The interaction between HIF-1α and tyrosine hydroxylase (TH) forms a crucial bridge to understanding its role in Parkinson’s disease." (PMID 40999534, 2025). "In summary, our findings demonstrated that IIM can alter PD-like pathology in mice, with microglial HIF-1α emerging as a potential target for the regulation of IIM in Parkinson's disease." (PMID 38555419, 2024). "For example, increased HIF1α levels typically determined in age-related and neurodegenerative pathologies, e.g., Alzheimer’s and Parkinson’s diseases, have been indicated as a clear sign of advanced disease progression." (PMID 34203691, 2021). "This review explores the link between hypoxia and Parkinson’s disease as well as promising new therapeutic strategies based on HIF-1α, a protein that controls the cellular response to hypoxia." (PMID 34439955, 2021). "There are numerous lines of evidence linking HIF-1α to Parkinson’s disease (PD)." (PMID 36009412, 2022). "Intriguingly, in one of the reported cases of this co-existence, the levels of HIF-1α in the tumor were markedly diminished, which are found to be elevated in pheochromocytoma patients without Parkinson’s disease." (PMID 41155475, 2025). "For example, activation of the STAT3/HIF1α axis promoted α-synuclein-induced ferroptosis, with GPX4 suppression and iron dyshomeostasis in a Parkinson’s disease model, whereas pharmacological STAT3 inhibition reduced lipid ROS and iron accumulation in microglia." (PMID 41304754, 2025). "Furthermore, the stabilization of HIF-1α by Lf leads to the induction of tyrosine hydroxylase (TH) and several neuroprotective factors, thereby enhancing neuronal viability against MPP+ toxicity in Parkinson’s disease." (PMID 38731800, 2024). "HIF-1α stabilization via HPH inhibition could thus be a potentialstrategy to upregulate therapeutically interesting genes relevant for neuroprotection, vascularization, and dopamine synthesis and it could have therapeutic potential in, for example, Parkinson's disease." (PMID 25006572, 2013).
liver diseases (19 papers, 2011 to 2025). "Intestine epithelial Hif1α deficiency exacerbates alcohol-associated liver disease by worsening gut barrier function." (PMID 39585307, 2024). "Our data provide evidence that pharmacological or genetic activation of intestinal HIF-1α markedly ameliorates western diet–induced metabolic dysfunction–associated steatotic liver disease in a sex-dependent manner." (PMID 39585307, 2024). "Hif1α has been found to be widely involved in the pathological response to a variety of liver diseases, especially those associated with hypoxia." (PMID 34853322, 2021). "RHCC also featured Succinivibrio (3.90%) and Treponema 2 overrepresentation, which are genera implicated in gut barrier dysfunction through succinate-driven HIF-1α activation and are associated with the progression of liver diseases and hepatic fibrogenesis through MMP-9 overexpression." (PMID 41239524, 2025). "The aim of this study was to determine whether pharmacological or genetic activation of intestinal HIF-1α ameliorates western diet–induced metabolic dysfunction–associated steatotic liver disease." (PMID 39585307, 2024). "Hypoxia is a major causative sensor and factor for deleterious oxidative stress in HS, and activation of HIF-1α is critically involved in the pathogenesis of liver diseases." (PMID 36164393, 2022). "Losartan is an angiotensin II receptor antagonist, that approved portal hypertension and related HIF-1α pathways in hepatic injury models." (PMID 34360607, 2021). "It is noteworthy that the transcriptional activity of NF-κB is critical for HIF-1α to contribute to hypoxic liver disease." (PMID 31455001, 2019). "HIF-1α affects liver disease by regulating genes involved in glucose and lipid metabolism." (PMID 40143173, 2025). "The HIF-1α signaling pathway plays a crucial role in alcohol-induced liver disease." (PMID 40894203, 2025). "Under the condition of liver hypoxia, HIF-1α may regulate liver gene coding, thereby affecting liver glucose transport and fructose production and further affecting the development of liver disease." (PMID 40143173, 2025). "Interestingly, intrahepatic HIF-1α expression seems to be a general phenomenon in ACLF across different etiologies and underlying liver diseases." (PMID 38338821, 2024). "Our early studies demonstrate that losartan decreased portal pressure and ameliorated hyperdynamic circulation on bile duct-ligated cirrhotic rats with portal hypertension and involvement of the HIF-1α and Wnt/β-catenin pathways on fatty liver graft with ischemia/reperfusion injury." (PMID 34360607, 2021). "In addition, HIF-1α protein can be further activated in several liver diseases, either by increasing oxygen consumption or by producing HIF-1α activators such as reactive oxygen species." (PMID 26098428, 2015). "We haven’t found direct evidences linking HIF3A gene with plasma ALT or liver diseases, but some studies on HIF1A, hypoxia or liver diseases may give some cues." (PMID 26717317, 2015). "In the present study, the hepatic expression and circulating levels of HIF-1α in patients with liver disease were investigated in order to elucidate the relationship between HIF-1α level and pathological characteristics, as well as the diagnosis and metastasis of HCC." (PMID 22224081, 2011). "In the present study, the expression and circulating levels of hepatic HIF-1α were investigated in patients with liver disease to prospectively elucidate the relationship between HIF-1α level and pathological characteristics, as well as the diagnosis and metastasis of HCC." (PMID 22224081, 2011). "This study describes the intra- and extrahepatic HIF-1α expression in different stages of liver disease, with a focus on its role in ACLF, with the aim of unraveling the possible mechanisms of intracellular HIF-1α induction." (PMID 38338821, 2024). "HIF-1α and HIF-2α are important modulators of inflammation, showing a pivotal role in the pathogenesis of several forms of liver disease." (PMID 29301219, 2017).
liver diseases (continued). "The levels of HIF-1α, vascular endothelial growth factor (VEGF), and angiopoietin-2 (Ang-2) expression in the sera of 220 patients with liver disease were quantitatively detected by ELISA." (PMID 22224081, 2011). "Three isoforms of the HIF-α subunit (HIF-1α, HIF-2α, and HIF-3α) have been described, and the overexpression of HIF-1α and HIF-2α has been detected in different liver diseases, including nonalcoholic fatty liver disease, alcoholic liver disease, radiation-induced liver injury, and HCC23." (PMID 30315182, 2018).